OCA2 (OCA2 melanosomal transmembrane protein)
Diseases named in the same sentence as OCA2 in open-access papers (continued):
Sharing a sentence is not in itself a finding about the gene and the disease.
Blindness (1 paper, 2013). Blindness is the condition of lacking visual perception defined as a profound reduction in visual perception. "In particular, loss-of-function for OCA2 can cause blindness due to loss of melanin from retinal pigment epithelial cells, and we speculate that natural selection for the APBA2 region in Europeans represents cell type-specific regulation that promotes fair skin while preserving visual function." (PMID 23555287, 2013).
Corneal astigmatism (1 paper, 2018). "Single marker-based association tests for corneal astigmatism identified four genome-wide significant loci (P < 5 × 10−8) near the genes ZC3H11B (1q41), LINC00340 (6p22.3), HERC2/OCA2 (15q13.1) and NPLOC4/TSPAN10 (17q25.3)." (PMID 30306274, 2018).
dwarfism (1 paper, 2022). "Other regions included novel candidate genes that might contribute to the phenotypic variation among the analyzed breeds, including genes for pigmentation-related traits (EDNRA, EDNRB, MITF and OCA2) and body size, with a strong candidate for dwarfism in rabbit (COL2A1)." (PMID 35062866, 2022).
encephalopathies (1 paper, 2025). "The genes NDN, SNRPN, and UBE3A are known for their association with Prader–Willi syndrome; GABRB and GABRA5 are associated with encephalopathies; OCA2 and HERC2 are linked to skin pigmentation." (PMID 40149731, 2025).
keratinocyte carcinoma (1 paper, 2024). A skin cancer arising from the keratin-producing cells of the epidermis. "Most of these genes are pigmentation-related genes (i.e., SLC45A2, TYR, OCA2, MC1R, and ASIP) and have a biological importance of lighter pigmentation in susceptibility to keratinocyte carcinoma." (PMID 38182794, 2024).
oculocutaneous albinism type IA (1 paper, 2015). "The combination of tools resulted in the indication of four, two and one nsSNPs as the most deleterious mutations in the TYR, TYRP1 and P proteins of the gene, which are associated with oculocutaneous albinism type IA (OCA1A), type III (OCA3) and type II (OCA2), respectively." (PMID 25794181, 2015).
papillary thyroid carcinoma (1 paper, 2022). "Then, we detected the protein expression of RGS8, DGKI and OCA2 in five pairs of papillary thyroid carcinoma tissues and found that their expression levels were obviously lower than those of the paired normal thyroid tissues." (PMID 36059514, 2022).
Prader-Willi-like syndrome (1 paper, 2024). "For example, MAGEL2 deletion has been associated with Prader-Willi-like syndrome (ORPHA ID:398,069), including a UPD case (ORPHA ID:98,754) with a role for the SNRPN, OCA2, MAGEL2, and NDN genes." (PMID 38902749, 2024).
Rubinstein-Taybi syndrome 1 (1 paper, 2025). "This includes a complex rearrangement of OCA2 (MIM# 611409) with deep intronic breakpoints and deletion of the second exon of CREBBP (MIM# 600140) in a child with features of Rubinstein-Taybi syndrome 1 (MIM#180849) and previous negative ES." (PMID 39763557, 2025).
thyroid cancer (1 paper, 2022). "To investigate the role of RGS8, DGKI and OCA2 expression, we explored the relationship between RGS8, DGKI, and OCA2 expression and clinical features in thyroid cancer patients, and the expression data were obtained from TCGA." (PMID 36059514, 2022). "To further investigate the significance and mechanism of RGS8, DGKI and OCA2 in thyroid cancer, we summarized the relationship between RGS8, DGKI and OCA2 expression and clinical features in the TCGA database of THCA patients." (PMID 36059514, 2022). "Our results revealed that the expression of RGS8, DGKI, and OCA2 in thyroid carcinoma was negatively correlated with multiple types of immune cell infiltration, including dendritic cells (DCs and aDCs), macrophages and neutrophils." (PMID 36059514, 2022). "In addition, RGS8, DGKI, and OCA2 were expressed at low levels in thyroid cancer in our sequencing results, GSE33630 and GSE29265." (PMID 36059514, 2022).
X-linked ocular albinism (1 paper, 2019). "Six genes are associated with autosomal recessive OCA (TYR, OCA2, TYRP1, SLC45A2, SLC24A5 and LRMDA), and one gene, GPR143, is associated with X-linked ocular albinism (OA)." (PMID 30679655, 2019).
tumor (33 papers, 2008 to 2025). "The DNA methylation level of OCA2 was expressively elevated in the THCA tumor tissue compared with that in normal tissue." (PMID 36059514, 2022). "By quantifying ssGSEA in the THCA tumor environment, we applied the Spearman correlation to prove the correlation between the level of immune cell infiltration and the expression of RGS8, DGKI and OCA2." (PMID 36059514, 2022). "Then, we used qRT–PCR and a Western blot analysis to detect the expression of RGS8, DGKI and OCA2 in tumor tissues and corresponding noncancer tissues from THCA patients." (PMID 36059514, 2022). "Similarly, by analysing RGS8, DGKI, and OCA2 expression in the TCGA database, we found that their expression in 58 THCA tumor samples was lower than that in 58 paired normal samples." (PMID 36059514, 2022).
cancer (27 papers, 2011 to 2025). A tumor composed of atypical neoplastic, often pleomorphic cells that invade other tissues. "First, we conducted a haplotype analysis adjusted for sex and family history of cancer for the variants of the OCA2 and HERC2 genes and a separate analysis for the variants of the MC1R gene." (PMID 40429816, 2025). "First, using TISIDB, we analysed the relationship between the expression levels of RGS8, DGKI and OCA2 and the level of immune cell infiltration in different cancers." (PMID 36059514, 2022). "We discovered that the DNA methylation level of OCA2 in cancer tissues was significantly higher than that in normal samples, suggesting that the high methylation level of OCA2 may be a reason for the low expression of OCA2 in THCA." (PMID 36059514, 2022). "We first evaluated RGS8, DGKI, and OCA2 expression across cancers." (PMID 36059514, 2022). "The DNA methylation level of OCA2 in cancer tissues was higher than that in the normal samples." (PMID 36059514, 2022). "Genes at two of these loci, HERC2/OCA2 and IRF4, are involved in pigmentation, while the third, CLPTM1L/TERT, is a known cancer driver." (PMID 40495383, 2025). "However, the relationship between OCA2 and other carcinomas has not been reported." (PMID 36059514, 2022).
OCA2 also shares sentences with these, for which no sentence is quoted: infection (55 papers); viral infection (14); COVID-19 (9); malaria (8); lupus (6); prostate carcinoma (6); Alzheimer disease (3); asthma (3); atherosclerosis (3); co-infection (3); colon cancer (3); dementia (3); depression (3); Genetic Disorders (3); glioma (3); psychosis (3); pyelonephritis (3); Chediak-Higashi syndrome (2); chronic periodontitis (2); Cirrhosis (2); Cognitive impairment (2); coronary artery disease (2); cystitis (2); dyslipidemia (2); endothelial dysfunction (2); gingivitis (2); Griscelli syndrome (2); Hepatitis (2); Hermansky-Pudlak syndrome (2); Lambert-Eaton myasthenic syndrome (2).
A further 145 diseases each share a sentence with OCA2 in 2 papers or fewer.